FARSA (phenylalanyl-tRNA synthetase subunit alpha)
Synonyms: FARSL; FARSLA; CML33; FRSA; PheHA; RILDBC2
Tractability: Small molecule: a structure with a bound ligand is known; it has a high-quality binding pocket. PROTAC: ubiquitination databases record sites on it; its protein half-life has been measured.
Target class: Enzyme; Ligase
Gene: Protein-coding gene on chromosome 19 (12,922,276 to 12,934,037, reverse strand). Ensembl gene ENSG00000179115.
Subcellular location: Cytoplasm
Subcellular location (Human Protein Atlas): Cytosol
Pathways (Reactome):
Metabolism of proteins: Cytosolic tRNA aminoacylation
Gene Ontology:
Molecular function: phenylalanine-tRNA ligase activity; protein binding; RNA binding; magnesium ion binding; aminoacyl-tRNA ligase activity; ATP binding; nucleotide binding; tRNA binding
Biological process: phenylalanyl-tRNA aminoacylation; protein heterotetramerization; tRNA aminoacylation
Cellular component: membrane; phenylalanine-tRNA ligase complex; cytoplasm; cytosol
Genetic constraint (gnomAD): Loss-of-function variants: 35 observed, 59.16 expected, observed/expected ratio (o/e) 0.59, 90% interval 0.45 to 0.78. The upper end of that interval is the gene's LOEUF score, 0.78, which puts it in group 3 of 6, group 1 being the genes least tolerant of losing a copy. Missense variants: 586 observed, 647.8 expected, observed/expected ratio (o/e) 0.9, 90% interval 0.85 to 0.97. Synonymous variants: 296 observed, 269.92 expected, observed/expected ratio (o/e) 1.1, 90% interval 1 to 1.21.
Homologues: Orthologues: chimpanzee FARSA (97% identical), macaque FARSA (96% identical), pig FARSA (95% identical), guinea pig FARSA (93% identical), mouse Farsa (93% identical), rat Farsa (86% identical), zebrafish farsa (76% identical), tropical clawed frog farsa (75% identical), dog FARSA (69% identical), Drosophila melanogaster alpha-PheRS (61% identical), Caenorhabditis elegans fars-1 (57% identical). Paralogues in human: FARS2 (16% identical), FDXACB1 (11% identical).
Diseases named in the same sentence as FARSA in open-access papers:
FARSA is named in the same sentence as 21 diseases in open-access papers, as found by Europe PMC text mining. Sharing a sentence is not in itself a finding about the gene and the disease. The quoted sentences say what the papers report.
melanoma (3 papers, 2020 to 2021). A malignant, usually aggressive tumor composed of atypical, neoplastic melanocytes. "In melanoma cells it has been demonstrated that in hypoxic conditions, EV exhibit a miRNome and proteome signature (AKR7A2, DDX39B, EIF3C, FARSA, PRMT5, VARS), which is associated with poor prognosis for the patients." (PMID 34439311, 2021). "Hypoxic melanoma EVs carried a hypoxic signature consisting of six proteins (AKR7A2, DDX39B, EIF3C, FARSA, PRMT5, VARS) which were significantly associated with a poor prognosis for melanoma patients." (PMID 32183388, 2020).
diffuse large B-cell lymphoma (2 papers, 2023 to 2025). "Compared with normal tissues, FARSA was upregulated in diffuse large-B cell lymphoma (DLBCL), in line with what has been reported." (PMID 36675119, 2023). "FARSA is involved in the pathobiology of MCL, where it is generally downregulated and also shows a tumor suppressor-like profile in diffuse large B-cell lymphoma." (PMID 40404986, 2025).
interstitial lung disease (2 papers, 2023 to 2024). A diverse group of lung diseases that affect the lung parenchyma. "Autosomal recessive inheritance of pathogenic variants of FARSA or FARSB can result in defective FARS1 which are characterized by interstitial lung disease, liver disease, brain abnormalities, facial dysmorphism and growth restriction." (PMID 37833669, 2023). "FARSA deficiency can result in FARS1-related disorder, which is characterized by interstitial lung disease, growth delay, hypotonia, brain calcifications, and liver dysfunction." (PMID 37833669, 2023).
liver dysfunction (2 papers, 2022 to 2023). "Exome sequencing revealed novel compound heterozygous variants in FARSA, P347L and R475Q, from a patient who initially presented neonatal-onset failure to thrive, liver dysfunction, and frequent respiratory infections." (PMID 35918773, 2022).
hypothyroidism (1 paper, 2023). Abnormally low levels of thyroid hormone. "In our patient, hypothyroidism and obvious microcephaly (head circumference: 43 cm at the age of 13 months, < P3) with no abnormalities on brain magnetic resonance imaging are less frequent findings among other reported patients carrying FARSA mutations." (PMID 37833669, 2023).
lymphoma (1 paper, 2023). A malignant (clonal) proliferation of B- lymphocytes or T- lymphocytes which involves the lymph nodes, bone marrow and/or extranodal sites. "Herein, we found the lowest levels of FARSA in patients with MCL compared with other subtypes of lymphomas, and the same lower levels of FARSA were observed in chemoresistant MCL cell lines." (PMID 36675119, 2023). "To investigate the expression feature of FARSA in NHLs, we started with analysis of the clinical data on lymphoma tissues using GEPIA2 generated by the Cancer Genome Atlas (TCGA) project." (PMID 36675119, 2023).
mantle cell lymphoma (1 paper, 2023). Mantle cell lymphoma is a rare form of malignant non-Hodgkin lymphoma affecting B lymphocytes in the lymph nodes in a region called the ``mantle zone''. "FARSA, the alpha subunit of the phenylalanyl-tRNA synthetase is elevated across many cancer types, but its function in mantle cell lymphoma (MCL) remains undetermined." (PMID 36675119, 2023).
myeloid leukemia (1 paper, 2021). A clonal proliferation of myeloid cells and their precursors in the bone marrow, peripheral blood, and spleen. "Elevated mRNA levels of the human α-PheRS, FARSA, during the development of myeloid leukemia correlate with tumorigenic events." (PMID 33547043, 2021).
non-small cell lung carcinoma (1 paper, 2019). A group of at least three distinct histological types of lung cancer, including non-small cell squamous cell carcinoma, adenocarcinoma, and large cell carcinoma. "In non- small cell lung cancer a circRNA derived from exons of the FARSA gene and called circFARSA, was observed to be enriched in cancerous tissues." (PMID 31889077, 2019).
Sepsis (1 paper, 2025). Sepsis is defined as life-threatening organ dysfunction caused by a dysregulated host response to infection. "Key genes identified among these, such as FARSA, SVIL, LAMP2, and COL12A1, were found to be influenced by exercise in both burns and sepsis, suggesting their potential roles in exercise-mediated recovery processes." (PMID 40028316, 2025).
cancer (7 papers, 2018 to 2023). A tumor composed of atypical neoplastic, often pleomorphic cells that invade other tissues. "For instance, the transcriptional profile of FARSA is distinct from that of FARSB across different cancer types." (PMID 36675119, 2023). "In intestinal stem cells of Drosophila midguts, α-PheRS levels are naturally slightly elevated and human FARSA mRNA levels are elevated in multiple cancers." (PMID 35486661, 2022). "Not only because Notch plays important roles in many tumors, but also because FARSA mRNA levels are considerably upregulated in many tumors, this novel activity deserves more attention for cancer research." (PMID 35486661, 2022). "Specific aaRSs that are differentially upregulated across many cancer types include TARS1 (n = 23), DARS2 (n = 22), GARS1 (n = 21), YARS2 (n = 21), EPRS1 (n = 20), AIMP2 (n = 19), and FARSA (n = 18)." (PMID 33266490, 2020). "More interestingly, FARS2 is down-regulated in KICH, while the two paralog ARSs, FARSA and FARSB, are up-regulated in six and four cancer types, respectively." (PMID 30588513, 2018). "In fact, FARSA is not the only aaRS with noncanonical functions in human cancer." (PMID 36675119, 2023).
Tumor (4 papers, 2021 to 2025). "Based on these data, we revealed an unexpected tumor-suppressing role of FARSA and provided evidence of the FARSA-mediated regulatory network in MCL." (PMID 36675119, 2023). "Taken together, our study for the first time revealed a tumor-suppressor role of FARSA in MCL cells." (PMID 36675119, 2023). "All these findings pinpoint the way in which FARSA exerts an anti-tumor effect by modulating the cell cycle." (PMID 36675119, 2023). "Collectively, the phenotypes observed in the manipulated MCL cells further supported a tumor suppressor-like role of FARSA in MCL cells." (PMID 36675119, 2023). "Indeed, the immunoblots confirmed the upregulation of FOXO1 and RAG1 in FARSAKD Jeko cells, and overexpression of FARSA in Jeko and REC1 cells reversed their expression levels, thus supporting another activated tumor-promoting FOXO1-RAG1 signaling in the FARSA-manipulated MCL cells." (PMID 36675119, 2023). "In spite of the upregulation of FARSA, DLBCL patients with high FARSA at a cutoff-low of 15% showed higher survival rates than patients with low FARSA, implying a tumor suppressor-like role of FARSA in DLBCL." (PMID 36675119, 2023). "Altogether, this discovery, along with the low FARSA levels in MCL patients as well as the negative correlation between FARSA and CCND1, suggests that FARSA may serve as a tumor suppressor in MCL, and low FARSA levels may confer chemoresistant properties to MCL cells." (PMID 36675119, 2023).
FARSA also shares sentences with these, for which no sentence is quoted: breast carcinoma (1 paper); Burkitt lymphoma (1); follicular lymphoma (1); Hypoalbuminemia (1); infection (1); liver disease (1); microcephaly (1); primary effusion lymphoma (1); respiratory infections (1).